IL34 (interleukin 34)
Diseases named in the same sentence as IL34 in open-access papers (continued):
Sharing a sentence is not in itself a finding about the gene and the disease.
tumor (108 papers, 2013 to 2026). "In triple‐negative breast cancer (TNBC), Hippo–YAP/TAZ signaling enhances tumor‐associated macrophage (TAM) infiltration through the TAZ/IL‐34 axis, establishing an immunosuppressive environment that decreases the effectiveness of immune checkpoint therapies." (PMID 40895190, 2025). "Pro-inflammatory cytokines (IL-34) and anti-inflammatory cytokines (IL-35) along with tumour-associated macrophages affects the development of GC." (PMID 40416985, 2025). "Mechanistically, IL34 increases migration of monocyte-derived tumor-associated macrophages (MD-TAMs) in primary tumors and lung metastases through colony-stimulating factor 1 receptor (CSF1R)." (PMID 40538439, 2025). "For example, high baseline expression of CSF1R or its ligands (CSF1, IL-34) in the tumor microenvironment has been associated with better responses to CSF1R inhibitors." (PMID 40821795, 2025). "In a syngeneic mouse model, the IL34-enriched TME attracted more monocyte-derived tumor-associated macrophages (MD-TAMs), which negatively altered tumor immunity and vasculature, the two protumor features targeted by current RCC therapy." (PMID 40538439, 2025). "In ovarian cancer, the production of IL-34 by tumor cells was associated with the development of a malignant microenvironment and tumor progression." (PMID 38254773, 2024). "IL-34 modulates tumor-associated macrophage function, enhances local immune suppression, and promotes survival of cancer cells resistant to ICI treatment." (PMID 39235457, 2024). "CSF-1 (M-CSF) and IL34 were determined to be expressed by the malignant cell population and other tumor-associated cells." (PMID 39272914, 2024). "Tumor-derived IL-34 enhances tumor-associated M2-polarized macrophages that exhibit immunosuppression and promote tumor growth." (PMID 36798830, 2023). "High IL-34 expression is associated with poor survival rates and tumor recurrence in patients with HCC." (PMID 38081923, 2023). "Accumulating evidence indicates that interleukin-34 (IL-34), a cytokine produced by cancer cells, and/or TAMs act as a linker between induction of a tumor-associated immunosuppressive microenvironment and drug resistance." (PMID 36765929, 2023). "One of such molecules is interleukin-34 (IL-34), a cytokine produced by cancer cells, TAMs, and stromal cells, which acts as a linker between induction of a tumor-associated immunosuppressive microenvironment and chemo/immunotherapy resistance." (PMID 36765929, 2023). "CSF-1R act as cell-surface receptors for the cytokines CSF-1 and IL-34 that are secreted by tumor cells and can cause the recruitment of M2-macrophages to support tumorigenesis." (PMID 35455743, 2022). "IL‐34 was also potentially associated with tumor cell proliferation and chemoresistance in an autocrine manner." (PMID 35132816, 2022). "It has been shown that tumor cell-derived IL34 was implicated in therapy resistance and disease progression." (PMID 36532749, 2022). "inoculated BALB/c mice with tumor CT26 cells either deficient or over-expressing IL-34 and then treated the animals with anti-PD-1 antibody." (PMID 35837402, 2022). "The upregulation of IL‐34 was significantly associated with tumor size, tumor node metastasis (TNM) stage, and lymph node metastasis (LNM)." (PMID 32573824, 2020). "The overexpression of IL‐34 was significantly associated with tumor size (P < .05), tumor TNM stage (P < .05), and lymph node metastasis (P < .05)." (PMID 32573824, 2020). "In this context, it is of great interest to identify oncogenic mutations that lead to IL-34 and M-CSF production by cancer cells and its impact on the tumor microenvironment, therapeutic resistance." (PMID 29323162, 2018). "Tumor cells or tumor-associated stromal cells produce hematopoietic growth factors (CSF-1, GM-CSF, and IL-34) which increase the expansion of the monocyte-macrophage lineage." (PMID 28197019, 2017).
tumor (continued). "We report that IL-34 induces the generation of Mφ which a phenotype and functions similar to the ones of human tumor-associated macrophages (TAM)." (PMID 23409120, 2013). "Additionally, high IL-34 levels are linked to increased immunosuppressive Tregs and decreased cytotoxic T cells within the tumor, aiding tumor immune evasion and progression." (PMID 39457693, 2024). "Specifically, high level IL-34 not only promotes the proliferation, invasion and chemoresistance of cancer cells, but also reprograms tumor associated macrophages (TAMs) to acquire a specific phenotype affecting tumor progression." (PMID 37149693, 2023). "Fast-growing VSs expressed high M-CSF and IL-34 levels that could regulate the chemotaxis of tumor-associated macrophages (TAMs)." (PMID 35628268, 2022). "M-CSF, combined with IL-34, tumor associated macrophages (TAMs) were the novel biological markers for GC, which may provide new insight for both the diagnosis and cellular therapy of GC." (PMID 34803728, 2021). "However, there were some exceptions, such as in the breast luminal B and HER2 tumor subtypes, where high levels of IL-34 were associated with better survival and good prognosis." (PMID 33408768, 2021). "Our results also suggest that, in order to reverse tumor-associated immunosuppression mediated by myeloid cells, strategies based on the inhibition of M-CSF-R should be privileged to prevent the effects of both IL-34 and M-CSF." (PMID 23409120, 2013). "Importantly, cancer cells-derived IL-34 was found to increase frequencies of M2-polarized tumor associated macrophages which showed enhanced immunosuppressive and pro-tumorigenic functions at the tumor microenvironment." (PMID 29515691, 2018). "This analysis confirmed that IL34 has a major effect on the regulation of the tumor immune microenvironment in RCC patients." (PMID 40538439, 2025). "Of the 10 orthotopically implanted mice 2 underwent primary tumor resection, and after 2 additional weeks, tumor-derived lung metastases were collected (i.e., LateLM_Ctrl and LateLM_IL34-OE)." (PMID 40538439, 2025). "Different studies showed a positive correlation between IL34 and pro-tumor TAMs infiltration in primary tumors." (PMID 40538439, 2025). "Through paracrine and autocrine signaling, tumor cells and associated stromal elements often produce high levels of CSF1 or IL-34, activating CSF1R on circulating myeloid precursors and promoting their migration into the tumor." (PMID 40821795, 2025). "In the KIRC-TCGA cohort, increased IL34 expression was associated with reduced survival in RCC patients, increased tumor grade, and increased incidence of distant metastases." (PMID 40538439, 2025). "Cell communication analysis of the CSF1 signaling network revealed that most CSF-1/IL-34 signals were emitted by tumor cells, which were primarily received by TAMs, while the tumor cells also received autocrine CSF-1/IL-34 signals." (PMID 41365876, 2025). "CSF-1R also binds IL-34; elevated IL-34 and CSF-1R levels correlate with tumor progression and poorer survival." (PMID 40079009, 2025). "We found that IL-34 contributes to tumor growth by generating immunosuppressive Mfs in the tumor microenvironment, which also plays a role in resistance to chemotherapy, radiotherapy, and immunotherapy." (PMID 39856797, 2025). "On the other hand, IL-34 enhances anti-tumour immunity by activating effector T cells and promoting macrophage-mediated tumour cell killing." (PMID 40416985, 2025). "Recent research highlights the importance of crosstalk between Hippo/YAP signaling and the TAZ/IL‐34 axis, particularly in shaping the tumor immune microenvironment and influencing cancer therapy outcomes." (PMID 40895190, 2025). "Prior research has demonstrated that in NSCLC, IL-34 secreted by tumor cells can modulate the activity of TAM through AKT signaling activation, hence augmenting local immunosuppression and facilitating the survival of chemotherapy-resistant tumor cells." (PMID 40370720, 2025).
tumor (continued). "Reduced gastric IL-34 exacerbates GC progression, forming a self-reinforcing loop that fosters a tumour-promoting environment." (PMID 40416985, 2025). "scRNA-seq showed that the CSF-1R ligands (CSF-1 and IL34) as well as CSF-1R were primarily expressed in tumor cells and TAMs, with the highest expression of IL34/CSF-1 in GBM cells and the highest expression of CSF-1R in microglia." (PMID 41365876, 2025). "In both the KIRC-TCGA and the UroCCR cohorts, high IL34 expression correlated with an increased tumor stage, an increased incidence of distant metastases, and a reduced survival in patients." (PMID 40538439, 2025). "Further analysis revealed that tumor cells in the BI group secrete excessive IL34, which, through the IL34-CSF1R interaction, activates the ERK1/2 signaling pathway in TNF-α+ TAMs, subsequently promoting TNF-α secretion." (PMID 39865310, 2025). "Either GFP-Renca Ctrl or IL34-OE cells were orthotopically implanted for primary tumor generation (i.e., PT_Ctrl and PT_IL34-OE) or injected into the tail vein to study the TME of lung metastasis (i.e., IVLM_Ctrl and IVLM_IL34-OE)." (PMID 40538439, 2025). "Further research shows that inhibiting IL-34 in chemotherapy-resistant tumors markedly suppresses tumor proliferation." (PMID 40370720, 2025). "In accordance, the literature portrays IL34 as a cancer-promoting interleukin in OvCa, inducing the formation of tumor-associated macrophages (TAM), being the important part of a tumor microenvironment." (PMID 39456618, 2024). "To expand on these findings, we compared IL34 mRNA expression in normal and tumor tissues from patients with mucosal SCCs." (PMID 39619016, 2024). "In ductal pancreatic cancer, tumor circulating cells produce IL-34, which promotes the differentiation of myeloid progenitor cells into MDSCs." (PMID 39457693, 2024). "In esophageal squamous cell carcinoma, irradiation of tumor cells can activate the cGAS-STING pathway and promote IL-34 secretion, thereby promoting the polarization and recruitment of M2 macrophages and tumor cell survival." (PMID 39464890, 2024). "In vitro and in vivo studies indicated that IL-34/CSF-1R activation increased BrdU incorporation, colony forming abilities of breast cancer cells and tumor growth in mouse models." (PMID 38254773, 2024). "Our current study demonstrates that intrahepatic IL-34 and TAMs are associated with high HBV-DNA, in addition to small tumor size of HBV-HCC patients." (PMID 35347503, 2023). "The results showed that the IL34-OC+IgG group had significantly larger tumor volumes and a greater number of lung metastatic foci compared to the IL34-NC+IgG group." (PMID 38081923, 2023). "Interleukin-34 (IL-34) is a cytokine that is involved in the regulation of immune cells, including macrophages, in the tumor microenvironment (TME)." (PMID 36798830, 2023). "The IL-34KO tumors responded better to anti-PD-1 antibody therapy, as evidenced by reduced tumor sizes in comparison to the control IgG; however the favorable effects of PD-1 blocking were canceled out by IL-34, which is produced by tumor cells." (PMID 36798830, 2023). "In this review, we provide an overview of the current knowledge of the function and role of IL-34 in mediating tumor immunological resistance to ICIs in cancer." (PMID 36798830, 2023). "Serum IL-34 and MCSF, or intrahepatic IL-34, MCSF and CD68+ tumor associate macrophages (TAMs) were determined using ELISA or immunohistochemistry." (PMID 35347503, 2023). "Intra-hepatic IL-34 was associated with high HBV-DNA, HBeAg−, poor differentiation and small tumor size of HBV-HCC patients." (PMID 35347503, 2023). "IL-34 blockade with anti-PD-1 antibodies considerably inhibited tumor development with significant immune cell infiltration." (PMID 36798830, 2023).
tumor (continued). "In other studies focusing on HBV-related HCC, IL-34 has been shown to enhance HCC proliferation and development in vivo, with noticeable increases in tumor volume and weight in IL-34-treated mice." (PMID 38081923, 2023). "By contrast, PD-1 inhibition combined with an anti-IL-34 antibody remarkably suppressed tumor growth and weight." (PMID 36798830, 2023). "Intra-hepatic IL-34 was associated with high HBV-DNA, HBeAg−, poor tumor differentiation and small tumor size in HBV-HCC patients." (PMID 35347503, 2023). "IL-34 was increased by 1.3-fold in low differentiated HCC compared to that of high differentiation group (p < 0.05); as well as, 1.3-fold in intra-hepatic IL-34 production from small tumor size (≤ 5 cm) than that from big size tumor group (p < 0.05)." (PMID 35347503, 2023). "The findings described here also indicate that IL-34 facilitates the differentiation of immunosuppressive cells within the tumor microenvironment, leading to therapeutic resistance and poor outcomes in various cancers." (PMID 36765929, 2023). "In our current study, only circulating IL-34 is significantly decreased in HBV-HCC patients post-anti-tumor treatment, compared to pre-treatment." (PMID 35347503, 2023). "In the same model, combination therapy with anti-PD-1 and anti-CTLA-4 induced substantial tumor growth inhibition, which was further enhanced by anti-IL-34 treatment." (PMID 36765929, 2023). "Tumor cells themselves produce a variety of inflammatory factors and chemokines to recruit TAMs including IL-6, IL-8, and IL-34." (PMID 38138294, 2023). "Macrophages are relocated to tumor areas and differentiate into TAMs in response to various cytokines, such as IL-34, CSF1, members of VEGFs, and chemokines, such as CCL5 and CCL2." (PMID 37958467, 2023). "An IL-34KO CT26 tumor cell model was conducted to determine if tumor-derived IL-34 contributes to TME M1- and M2-predominant macrophage populations." (PMID 36798830, 2023). "Analysis of tumor-infiltrating immune cells also found a relation between IL-34 expression and type-2 immunosuppressive macrophages in different cancer types." (PMID 36798830, 2023). "Fetal component of hepatoblatoma secret IL34 which promote tumor proliferation and chemo‐resistance by autocrine manner." (PMID 35132816, 2022). "Especially, tumor cell-derived IL-34 reduced immunotherapy efficacy by modulating myeloid cell activity." (PMID 36532749, 2022). "Targeting IL-34 in chemoresistant tumors resulted in a marked inhibition of tumor growth when accompanied with chemotherapy." (PMID 35837402, 2022). "By immunohistochemistry, we also demonstrated that IL-34 was mostly produced by cancer cells and to lesser extent by tumor-infiltrating mononuclear cells." (PMID 35837402, 2022). "Collectively, these findings indicate that IL-34, produced by cancer cells as well as additional cell types present in the tumor mass, interferes with immunotherapy by limiting T cell accumulation and favouring the anti-inflammatory environment." (PMID 35837402, 2022). "Multiple cytokines and chemokines, including CXCL12, CXCL16, interleukin (IL)-1β, IL-6, IL-34, macrophage colony-stimulating factor (M-CSF), and tumor necrosis factor-α (TNF-α), are also associated with tumor progression and hearing disturbance." (PMID 35628268, 2022). "To investigate the mechanism of IL‐34 overexpression in tumor cells, we next stimulated Huh6 cells with several cytokines that are considered to be secreted from macrophages." (PMID 35132816, 2022). "Meanwhile, cytokines such as IL-6 and IL-10 can further stimulate the secretion of IL-34 by tumor cells and immune cells and promote the expression of IL-34." (PMID 35936748, 2022). "High IL‐34 expression is correlated with high infiltration of TAMs in the tumor microenvironment, and patients with high IL‐34 expression and high TAM density have a worse prognosis with shorter overall survival and recurrence‐free period." (PMID 35132816, 2022).
tumor (continued). "They showed that IL-34-knockout tumors exhibited a better response when treated with anti-PD-1 antibody whereas the significant effect of PD-1 blockade was abrogated by the existence of IL-34 secreted by tumor cells." (PMID 35837402, 2022). "PD-1 and CTLA-4 combination therapy induced substantial tumor suppression, which was markedly enhanced by anti-IL-34 treatment." (PMID 35837402, 2022). "Changes in IL-34 expression have also documented in various neoplastic diseases, where the cytokine is supposed to either limit or enhance the carcinogenetic processes." (PMID 34535634, 2021). "In the tumor tissues of patients with high IL-34 expression, the proportion of these immune cells was higher except for that of activated CD4+ memory T cells." (PMID 34336646, 2021). "Once within the tumor, growth factors expressed by the tumor (M-CSF, IL-34, TGF-b, and IL-10) induce an immunosuppressive macrophage phenotype (M2 macrophages)." (PMID 33917061, 2021). "Within the tumor, monocytes differentiate into immunosuppressive macrophages via the CSF1R pathway in response to M-CSF and potentially IL-34 secretion by tumor cells." (PMID 34178677, 2021). "IL-1b and IL34, which were induced by Pparγ1 are also known to induce a pro-tumorigenic tumor microenvironment (TME) with IL-34 enhancing recruitment and survival of TAM." (PMID 33946495, 2021). "The emergence of a population resistant to the BRAF inhibitor was associated with an increase in CSF-1R and IL-34 expression, and activation of ERK1/2 and AKT signaling pathways to promote tumor survival and proliferation." (PMID 33408768, 2021). "There is also evidence that IL-34 plays a role in tumorigenesis given its ability to stimulate endothelial cell proliferation and recruitment of macrophages into the tumor tissue." (PMID 33800170, 2021). "Representative tumor images demonstrated that juglone significantly inhibited IL-34-induced mammary gland tumor development." (PMID 33800170, 2021). "Growing evidence has shown that the release of molecules, such as IL-6, IL-10 and IL-34 by TAMs, contributed to the acquisition of a chemo/radioresistant phenotypes in tumor cells." (PMID 34830817, 2021). "IL-34 can recruit tumor-associated macrophages, which drive the formation of new blood vessels in cancer; hence, IL-34 is assumed to promote tumor progression." (PMID 34336646, 2021). "IL-34 favored tumor cell proliferation and metastasis by promoting IL-34-derived macrophage extravasation and polarization into a TAM M2 phenotype." (PMID 33408768, 2021). "In tumour areas, IL-34 was mostly produced by cancer cells and to lesser extent by mucosal mononuclear cells." (PMID 34535634, 2021). "We have shown in our previous reports that targeting IL-34 in chemo-resistant tumors in vitro resulted in a remarkable inhibition of tumor growth." (PMID 33072227, 2020). "Interleukin (IL)‐34 is a recently discovered pro‐inflammatory cytokine and is a vital regulator in different tumor types." (PMID 32573824, 2020). "Taken together, these data show that IL‐34 participates in tumor progression via the EMT phenotype in PTC cells." (PMID 32573824, 2020). "Accumulating evidence demonstrates that IL‐34 also plays an important role in tumorigenesis based on its effect on promoting endothelial cell proliferation and transportation of macrophages into tumor cells." (PMID 32573824, 2020). "Several studies have also concentrated on the contribution of IL‐34 in cancer and demonstrated that IL‐34 plays a pro‐tumorigenic role in the tumor microenvironment." (PMID 32573824, 2020). "When JQ1 was administered into an in vivo tumor model, both Il34 expression and tumor growth were suppressed." (PMID 33072227, 2020). "The median expression of IL-34 differed significantly with age, gender and tumour differentiation of GC patients." (PMID 32765828, 2020).